MYC (MYC proto-oncogene, bHLH transcription factor)
Diseases named in the same sentence as MYC in open-access papers (continued):
Sharing a sentence is not in itself a finding about the gene and the disease.
Burkitt lymphoma (continued). "Transcriptome analysis has shown that the MYC signature is the hallmark signaling difference between Burkitt's lymphomas and diffuse large B-cell lymphomas with: upregulation of MYC-target genes and downregulation of genes involved in the NF-kB and interferon responses." (PMID 24586784, 2014). "Indeed, MYC is the most frequently amplified human oncogene and its activation by chromosomal translocation is a hallmark of Burkitt lymphoma." (PMID 22039435, 2011). "The MYC mutation profile, in those cases, is consistent with the one found in Burkitt Lymphoma (BL), where almost all the cases are characterized by the same translocation." (PMID 41008653, 2025). "Endemic Burkitt lymphoma (BL) is a childhood cancer in sub-Saharan Africa characterized by Epstein–Barr virus and malaria-associated aberrant B-cell activation and MYC chromosomal translocation." (PMID 36878637, 2023). "In addition, the GQC-05 analogue of ellipticine was recently shown to bind with high affinity and selectivity the G4 structure within the NHE III1 region of MYC in vitro and caused down-regulation of MYC mRNA expression levels in a Burkitt’s lymphoma cell line." (PMID 24108400, 2013). "Immunohistochemistry confirmed B-cell lineage (CD20, CD10, BCL6, c-MYC) with a Ki-67 index of 95%, consistent with Burkitt lymphoma." (PMID 42051830, 2026). "Multiparameter optimization yielded compound 18, which demonstrated improved efficacy in a MYC-dependent Burkitt lymphoma xenograft model at a significantly lower dose than the RUVBL1/2 inhibitor CB-6644." (PMID 42017951, 2026). "In Burkitt’s lymphomas, oncogenic MYC and LAT1/LAT3 transporters create positive feedback called MYC-LAT1/LAT3." (PMID 41008653, 2025). "In EBV-driven cancers, such as in Burkitt lymphoma, MYC overexpression, driven by chromosomal translocations, further enhances cell proliferation and contributes to tumorigenesis." (PMID 40354417, 2025). "Laboratory results were unremarkable, and biopsy confirmed Burkitt lymphoma based on c-MYC positivity and the characteristic “starry sky” appearance, leading to the initiation of chemotherapy." (PMID 41191884, 2025). "Burkitt lymphoma (BL) is an aggressive non‐Hodgkin B‐cell lymphoma characterised by chromosomal translocations involving the MYC gene, leading to its overexpression and driving uncontrolled proliferation." (PMID 40572059, 2025). "One of the defining features of Burkitt lymphoma is the presence of a characteristic chromosomal translocation involving the MYC oncogene on chromosome 8." (PMID 41180747, 2025). "When the c-MYC gene translocates from chromosome 8 to chromosome 14, it results in uncontrolled B-cell growth, driving the development of Burkitt lymphoma." (PMID 41180747, 2025). "LN contained one single atypical follicle with Burkitt lymphoma morphology and harboring IGH::MYC fusion consistent with the diagnosis of incipient Burkitt Lymphoma." (PMID 40616614, 2025). "Additionally, a fair amount of MYC‐regulated and nuclear factor‐kappa B pathway associated miRNAs was useful in differentiating between Burkitt lymphoma (BL) and DLBCL." (PMID 39846133, 2025). "GPM identified IGL::MYC, which is observed in 10–20% of Burkitt lymphoma cases, providing further support for a diagnosis of Burkitt lymphoma." (PMID 41374977, 2025). "We found that an H-DNA-forming sequence from a translocation breakpoint hotspot in the c-MYC gene in Burkitt lymphoma accumulated higher levels of 8-oxodG lesions than canonical B-DNA-forming sequences." (PMID 39950343, 2025).
Burkitt lymphoma (continued). "Knockdown of c-MYC following the addition of Doxycycline (Dox) to the murine Burkitt lymphoma cell line, P493-6, in vitro also led to a significant (p < 0.05) decrease in c-MYC and PA2G4 protein expression over 96 h." (PMID 41002386, 2025). "In an in vivo study, the liver of hu-PBMC-CDX mouse showed less tumor cell infiltration compared to the control, along with decreased expression levels of EZH2 and c-MYC, indicating that dEZH2 effectively suppresses Burkitt’s lymphoma." (PMID 40308579, 2025). "Following this discovery, MYC translocations were described in Burkitt lymphoma, where MYC is juxtaposed to immunoglobulin enhancers." (PMID 40488968, 2025). "Such a high threshold is based on the biology of Burkitt lymphoma, characterized by rapid cell turnover and high cellular proliferation, driven by MYC oncogene overexpression." (PMID 40428800, 2025). "A major area of progress involves the development of targeted therapies directed at the MYC oncogene, which drives the aggressive growth characteristic of Burkitt lymphoma." (PMID 41180747, 2025). "Burkitt lymphomas are known to be positive for c-MYC in nearly all cases, whereas only a tiny number of DLBCLs express this marker." (PMID 40428800, 2025). "The molecular hallmark of Burkitt lymphoma (BL) is a chromosomal translocation that involves the MYC gene and immunoglobulin loci, resulting in the deregulated expression of MYC, an oncogenic transcription factor that appears deregulated in about half of human tumors." (PMID 39766110, 2024). "Another study showed that HSP90 inhibitors were synergistic with dual PI3K/mTOR inhibition in Burkitt lymphoma driven by MYC dysregulation." (PMID 38475728, 2024). "Several investigators revealed that this increased consumption of glucose is due to the oncogenic levels of MYC, as evidenced in Burkitt’s lymphoma and MYC-driven liver carcinoma." (PMID 38390324, 2024). "NUDT1 depletion similarly elicited robust apoptosis in MYC-overexpressing Burkitt’s lymphoma P493 cells, while administration of tetracycline (Tet) to repress MYC expression significantly inhibited cell death." (PMID 38493213, 2024). "Certain lymphoma subtypes are associated with distinct acquired genetic abnormalities, such as translocation of the BCL2 oncogene in follicular lymphoma or translocation of the MYC oncogene in Burkitt lymphoma." (PMID 38672546, 2024). "The combination of c-MYC translocations and specific viral mechanisms results in the characteristic rapid proliferation of Burkitt’s lymphoma." (PMID 39772235, 2024). "It has been reported that by repressing miR-26a, MYC stimulates EZH2 expression in Burkitt lymphoma cells, highlighting how EZH2 deregulation is interconnected with c-MYC-driven tumorigenesis." (PMID 39769907, 2024). "We address this gap by measuring mutation frequencies in obese and normal-weight transgenic reporter mice carrying either a control human B-DNA- or an H-DNA-forming sequence (from a translocation hotspot in c-MYC in Burkitt lymphoma)." (PMID 39043652, 2024). "Inhibition of HSP90 suppresses MYC expression in MYC-driven Burkitt lymphoma and BTKi-resistant MCL." (PMID 38326887, 2024). "S63845 displayed impressive potency at low nanomolar concentrations in preclinical in vitro and in vivo models of hematological malignancies, including MM, AML, CML, and c-MYC-driven Burkitt lymphoma." (PMID 38666914, 2024). "These three cell lines are derived from Burkitt lymphomas, where MYC translocation drives MYC expression." (PMID 38475709, 2024). "The HIV Tat protein enhances the activity of the c-MYC gene promoter by binding to AP-1, thereby contributing to a more aggressive phenotype in HIV-associated Burkitt lymphoma." (PMID 39329948, 2024). "As for Burkitt’s lymphoma, Ig genes are the most frequent MYC partners, but they can also translocate in 35–50% with BCL6, BCL2, PAX5, or even IKZK1." (PMID 39594704, 2024).
Burkitt lymphoma (continued). "The first implication of c-MYC in human cancer arose with the identification of the MYC gene translocation to the IGH locus in human Burkitt lymphoma (BL)." (PMID 39594704, 2024). "In a MYC-inducible human Burkitt lymphoma model P493 cell line, glutamine entered the TCA cycle and contributed to citrate carbons under hypoxia and to fumarate, malate, and citrate under glucose deprivation." (PMID 36797531, 2023). "As early as 1981, scientists proposed for the first time that the integration of virus promoter can drive the expression of cell MYC (c-Myc) and lead to cancer, and MYC was first found in human Burkitt lymphoma in 1982." (PMID 36966168, 2023). "We have analyzed the translocation break points at the exon 1/intron 1 of c-MYC locus from patients with Burkitt’s lymphoma." (PMID 37926284, 2023). "Approximately 70% of cancers express high levels of MYC, owing to chromosomal translocations (e.g., in Burkitt lymphoma), genomic amplifications or oncogenic signals." (PMID 36342579, 2023). "The role of MYC in human tumorigenesis was exemplified by the translocated MYC coding sequences downstream from the immunoglobulin heavy chain enhancer in Burkitt lymphomas." (PMID 37601651, 2023). "The in vitro and in vivo potential of the tool compound S63845 was explored in pre-clinical studies in haematological malignancies, such as MM, AML, CML, and c-MYC-driven Burkitt lymphoma." (PMID 36342579, 2023). "Several long noncoding transcripts were originally identified in the human B cell line P496-3 and then shown to be required for MYC-driven proliferation of Burkitt lymphoma-derived RAMOS cells." (PMID 36849510, 2023). "The classic example of a MYC-driven tumor is Burkitt lymphoma in which a chromosomal translocation brings the expression of MYC under the control of the immunoglobin heavy chain locus." (PMID 36849510, 2023). "FISH showed positive MYC expression in three patients, including eight with advanced B-cell lymphoma with 11q abnormalities and three with Burkitt's lymphoma with 11q abnormalities." (PMID 38185522, 2023). "A recent study revealed that c-MYC-driven human Burkitt lymphoma cells were eradicated by targeting MCL-1." (PMID 37570631, 2023). "We evaluated the role of MYC overexpression by knocking down MYC expression in P493-6 Burkitt lymphoma cells." (PMID 36792656, 2023). "This technology has been also applied to inhibit BRD4 in Burkitt’s lymphoma cell lines, leading to MYC depletion accompanied by tumor regression in a xenograft model." (PMID 36969025, 2023). "Consistently, a study indicated that MYC expression was significantly suppressed after FACT subunit knockout to maintain the latency of Epstein‒Barr virus (EBV)-infected Burkitt lymphoma (BL)." (PMID 36691066, 2023). "Translocation of the MYC gene (8q24) to the immunoglobulin heavy chain locus (14q32) that leads to its overexpression is detected in approximately 85% of Burkitt lymphoma cases." (PMID 35563017, 2022). "In Burkitt lymphoma, MYC can stimulate enhancer of zeste homolog 2 (EZH2) expression by suppressing its negative regulator miR-26a." (PMID 35120580, 2022). "To this end, we analyzed the MYC mRNA expression in Ramos cells, a human Burkitt’s lymphoma cell line that showed a resistance to chemotherapeutic drugs, in the presence or absence of IBtkα." (PMID 35216159, 2022). "Burkitt's lymphoma (BL) is characterized by a translocation between chromosomes 8 and 14 resulting in an overexpression of the MYC oncogene." (PMID 35911302, 2022). "This is exemplified by Burkitt’s lymphoma, where the MYC gene on chromosome 8 is translocated next to the IGH locus on chromosome 14; this triggers its overexpression." (PMID 36291894, 2022). "In this study, we performed a search and functional analysis of eRNAs in the IGH locus expressed in Burkitt lymphoma cells and capable of stimulating the expression of the MYC gene." (PMID 35563017, 2022).
Burkitt lymphoma (continued). "In particular, duplications and/or translocations of the MYC gene are frequently observed in numerous human cancers, such as Burkitt’s lymphoma and multiple myeloma." (PMID 35216159, 2022). "The increased expression of the MYC proto-oncogene due to IGH/MYC translocation is detected in approximately 85% of Burkitt lymphoma cases." (PMID 35563017, 2022). "In particular, we found that the IBtkα silencing triggered the downregulation of both MYC mRNA and protein expression, as well as a strong decrease of cell survival, mainly through the induction of apoptotic events in Burkitt’s lymphoma cells." (PMID 35216159, 2022). "Another study notes that let-7a down-regulates MYC and reverts MYC-induced growth in Burkitt lymphoma cells." (PMID 35328182, 2022). "This paradoxical loss of c-MYC has been observed in multiple myeloma, Hodgkin lymphoma, and in the c-MYC–addicted B-cell neoplasm Burkitt lymphoma, although its mechanistic explanation remained elusive." (PMID 36846090, 2022). "In our λc-MYC (Avy/a) model mouse of Burkitt lymphomas, we repeatedly obtained a complex electrophoretic pattern on Western blot, notably in lymph node tumors." (PMID 35740961, 2022). "In contrast to Burkitt lymphoma (BL), where MYC is almost exclusively fused to an immunoglobulin locus, up to 50% of MYC translocations in DLBCL involve non-immunoglobulin genes, including among others BCL6, PAX5, and IKZF1." (PMID 35060000, 2022). "SUMOylated hnRNP K at Lys422 also positively regulates MYC expression at the translational level, contributing to Burkitt’s lymphoma cell proliferation." (PMID 36452487, 2022). "In this context, an exhaustive study of c-MYC transcripts in Burkitt lymphoma patients as well as in other animal models becomes necessary." (PMID 35740961, 2022). "Overexpression and knockdown of our primary candidate eRNA AL928768.3 led to the corresponding changes in the expression of MYC proto-oncogene in Burkitt lymphoma cells." (PMID 35563017, 2022). "This translocation deregulates MYC expression, contributing to Burkitt’s lymphoma cell proliferation." (PMID 36452487, 2022). "A study conducted in immunodeficient mice bearing subcutaneous xenografts of Raji Burkitt lymphoma demonstrated that pelabresib inhibits the expression of MYC in tumor tissue in a dose-dependent manner." (PMID 36923307, 2022). "Virtually all Burkitt lymphoma cell lines show a rearrangement between the c-MYC locus and one of the immunoglobulin gene loci." (PMID 35740961, 2022). "BRD4 belongs to BET family member and preclinical studies with BRD4 inhibitors demonstrate the suppression of MYC expression in MYC-driven Burkitt’s lymphoma cell lines." (PMID 36465385, 2022). "For example, the dominance of c-MYC, which is silent in normal tissue, is abnormally activated in Burkitt lymphoma cells as a result of aberrant alternative promoter (AP) usage at the MYC gene locus." (PMID 35111672, 2021). "Research in Burkitt lymphoma demonstrated a MYC-miR-150-ZDHHC11/B-MYB network, in which high levels of MYC repress miR-150, which leads to derepression of MYB, ZDHHC11 and ZDHHC11B, and promotes proliferation." (PMID 33593440, 2021). "Similar to PCNSL, Burkitt lymphoma, which is defined by a high MYC expression, has a high affinity for the CNS." (PMID 34944954, 2021). "In Burkitt lymphoma, MYC suppressed POX/PRODH expression and increased P5CS and PYCR1, leading to reprogramming of proline and glutamine metabolism." (PMID 33465163, 2021). "DAC also inhibited the growth of Burkitt lymphoma (BL) cells by regulating MYC and its relevant pathways." (PMID 34222013, 2021). "This occurs in essentially all Burkitt’s lymphoma where the MYC gene on chromosome 8 is translocated into one of several heavy and light chain immunoglobulin loci on chromosome 14 (i.e., t(8:14) translocation), driving high levels of MYC expression." (PMID 33799592, 2021). "Induction of lytic infection in Burkitt lymphoma cells was correlated with decreased MYC expression." (PMID 34572593, 2021).
Burkitt lymphoma (continued). "Perhaps the most common EBV-induced change to MYC expression is in the form of a common MYC gene translocation event in EBV-positive Burkitt’s lymphoma." (PMID 34066504, 2021). "When a panel of BLBCL, Hodgkin and Burkitt lymphoma cell lines were compared to GCB cells it was revealed that MYC, ZDHHC11/B and MYB were upregulated and miR-150 was downregulated in all lymphoma types as compared to GCB." (PMID 34502399, 2021). "MYC–IGH fusion sequences or IG rearrangements enable minimal disease detection in Burkitt lymphoma and -leukemia." (PMID 33921029, 2021). "Chromosomal translocation of MYC with the immunoglobulin locus was first observed in Burkitt’s lymphoma resulting in constitutive MYC expression, and was the basis for generation of the Eμ-myc mice." (PMID 33651821, 2021). "The dysregulation of these oncogenes drives B-cell hematological malignancies such as follicular lymphoma (BCL2 translocation, MLL2 inactivation) DLBCL (e.g. BCL6, BCL2 and MYC translocation) or Burkitt’s lymphoma (MYC translocation)." (PMID 33912162, 2021). "Here we use a combination of loss- and gain-of function approaches to interrogate the role of the MYC–HCF-1 interaction in the context of a canonically MYC-driven cancer—Burkitt lymphoma." (PMID 33416496, 2021). "Burkitt’s lymphoma (BL) is driven by a translocation that puts MYC expression under the regulation of an immunoglobin gene." (PMID 34577013, 2021). "Most cases of Burkitt lymphoma harbor translocations of the MYC gene, typically juxtaposing it with enhancer genes of the IGH locus, and less frequently the IGK and IGL loci resulting in upregulation of c-myc, its target genes and target microRNAs." (PMID 34956859, 2021). "An example of MYC gene alterations are point mutations that result in increased c-Myc protein stability and activity, as identified in the c-Myc-activating translocations in Burkitt’s lymphoma." (PMID 34503295, 2021). "There are rare reports of MCL with translocations involving CCND1 and IGK (chromosome 2) or IGL (chromosome 22) instead of IGH (chromosome 14), analogous to IGK/MYC or IGL/MYC translocations seen in Burkitt lymphoma." (PMID 34888236, 2021). "Analysis of a hybrid of rodent and human Burkitt lymphoma cells revealed the presence of a reciprocal translocation between chromosomes 8 and 14 that disrupted the MYC gene, which confirmed that MYC functions as an oncogene in humans." (PMID 33858415, 2021). "In Burkitt lymphoma, MYC-induced miR-19 inhibits the PI3K inhibitor PTEN, paving the way for lymphomagenesis." (PMID 34372899, 2021). "This compound also has a picomolar binding affinity and inhibits the proliferation of MYC-induced cancer cells (neuroblastoma and Burkitt’s lymphoma) and MLL1-rearranged leukemia by reducing MYC recruitment to the MYC/WDR5 target gene." (PMID 34201935, 2021). "Another example is the IGH-MYC fusion gene in Burkitt’s lymphoma, which drives c-myc overexpression owing to the juxtaposition of MYC with the strong enhancer of the immunoglobulin (Ig) gene." (PMID 34440406, 2021). "Burkitt lymphoma (BL) is a highly aggressive type of B-cell lymphoma characterized by the translocation of MYC, Epstein-Barr virus (EBV) infection, and Ki-67 proliferation index of ~100%." (PMID 33669569, 2021). "A clear example of this is Burkitt’s lymphoma wherein a chromosomal translocation results in constitutive activation of the MYC oncogene." (PMID 33912162, 2021). "Recurrent MYC translocations, either alone or in combination with BCL2 rearrangements, are the hallmark of Burkitt’s lymphoma and other mature B-cell neoplasms that are usually associated with an aggressive clinical behavior." (PMID 33651821, 2021). "Of note, clinical trials of the MCT1 inhibitor AZD3965 in diffuse large B cell lymphoma and Burkitt’s lymphoma, two typical MYC-driven cancer types, are currently ongoing." (PMID 32651356, 2020).